CD4 (CD4 molecule)
Diseases named in the same sentence as CD4 in open-access papers (continued):
Sharing a sentence is not in itself a finding about the gene and the disease.
HIV-1 infection (continued). "We also confirmed that TNF-α is significantly increased during HIV-1 infection in primary CD4+ T-lymphocytes." (PMID 24714696, 2014). "The CD4-Env interaction is crucial for viral entry, thus downregulation of CD4 surface expression or the use of competitor molecules that target this interaction can inhibit HIV-1 infection." (PMID 25423108, 2014). "First, in HIV-2 infection, CD4+ T-cells retain better proliferative capacity, remain less differentiated, and elicit more polyfunctional responses than in HIV-1 infection." (PMID 24803534, 2014). "In 6 donors, HIV-1 infection significantly depleted LP CD4+ T cells by 4 dpi relative to mock infection with DMSO." (PMID 24495380, 2014). "Given that high responses to V3 have been associated with a lower risk of HIV-1 infection among vaccinees who had low gp120-specific plasma IgA: (OR = 0.49, p = 0.007), we also performed a V3-specific analysis for CD8 and CD4 epitopes." (PMID 25350851, 2014). "It is therefore possible that HIV-1 infection itself results in changes in the conformation of LFA-1 on CD4+ T cells such that they express the S6F1 epitope to which LFA-1 MAb binds." (PMID 23594747, 2013). "Ex vivo analysis of eight pro- and anti-apoptotic molecules in chronic HIV-1 infection revealed that pro-apoptotic Bak was increased in CD4+ T cells and correlated directly with sensitivity to CD95/Fas-mediated apoptosis and inversely with CD4+ T cell counts." (PMID 24130482, 2013). "This contrasts with two studies of Prostratin's effect on HIV-1 infection of human CD4+ T-cells, which found that reverse transcription and HIV-1 p24 uptake was inhibited." (PMID 23201205, 2013). "Regarding the impact of HIV-1 infection on syphilis, studies have shown that it adversely affects the serologic response to syphilis treatment, especially at lower CD4 cell counts <200 cells/μL, but that CART reduces the failure rate." (PMID 26316953, 2013). "This activation/proliferation enhanced CCR5 expression in memory CD4+ T cells and rendered them more susceptible to CCR5-tropic wild-type HIV-1 infection than to vpr-deficient virus." (PMID 24339781, 2013). "In contrast, in LPS-mediated mature DC, BST-2/tetherin exerted a significant restriction in transfer of HIV-1 infection to CD4+ T cells." (PMID 23311681, 2013). "Chronic immune activation is a hallmark of HIV-1 infection and is likely to play a pivotal role in CD4+ T cell depletion during the course of HIV-1 infection." (PMID 23437155, 2013). "Although it appeared to require CD4 and R5 or X4 coreceptors, as for HIV-1 infection of LC, there was accumulating evidence that HIV-1 infected the DC by more than one pathway." (PMID 24278768, 2013). "During natural course of HIV-1 infection there is a gradual increase in HIV-1 RNA viremia in parallel with impairment on functional HIV-1-specific CD4+ and CD8+ T cell responses." (PMID 23516578, 2013). "Each of these treatments has been tested in mouse models and led to the production of modified HSCs which give rise to CD4+ T-cells that are resistant to R5 HIV-1 infection." (PMID 23364195, 2013). "It is generally believed that the main hurdle to virus eradication is the persisting HIV-1 infection in latent reservoirs, particularly in memory CD4+ T cells." (PMID 24086129, 2013). "In four of the five patients (patients 1, 2, 3 and 5) the HIV-1 infection frequency of memory CD4+ T-cells from lymph node tissue was 2–17 times higher than the infection frequency of memory CD4+ T-cells from peripheral blood." (PMID 23818847, 2013). "Doitsh and colleagues reported that the accumulation of reverse transcription intermediates in CD4 T cells undergoing abortive HIV-1 infection results in apoptotic death." (PMID 24455433, 2013). "Our results suggest a determinant role of contact between mDC and CD4+ T cells in immune activation and viral dissemination, which likely contribute to the pathogenesis of HIV-1 infection." (PMID 23590845, 2013).
HIV-1 infection (continued). "The HIV-1 infection is mediated by interaction between the proteins of the viral envelope, gp120 and gp41, and the receptor of T lymphocyte, CD4." (PMID 23841087, 2013). "Our study addresses cell-intrinsic differences between human and chimpanzee CD4+ T cells that can clarify differences in their ability to succumb to HIV-1 infection." (PMID 22945238, 2013). "Individuals with a homozygous (32 base pair) deletion in the coding region of the CCR5 gene (CCR5∆32/∆32), the co-receptor for (R5) tropic HIV-1 viral entry produce CD4+ progeny that are resistant to R5 tropic HIV-1 infection." (PMID 24284880, 2013). "Elevated levels of CCR5, the coreceptor for HIV-1, on CD4+ BAL T cells in comparison to peripheral blood cells suggest a local permissive environment for HIV-1 infection in human lungs." (PMID 23147374, 2013). "The single mutant variants of GRFT (each D30A, D70A or D112A mutant destroying one of the three carbohydrate-binding sites in GRFT) were ∼25- to 70-fold less potent to prevent cell-free HIV-1 infection of CD4+ T-lymphocytes." (PMID 23741304, 2013). "In the current study, we reported on the development of a new fully transgenic mouse model, hCD4/R5/cT1 mice, which supports in vivo replication of HIV-1 in the appropriate target cells for HIV-1 infection, CD4+ T cells and macrophages." (PMID 23691059, 2013). "Efforts to cure HIV-1 infection have focused on a small pool of CD4+ T cells that carry viral genetic information in a latent form." (PMID 23459007, 2013). "Whereas HIV-1 can infect a variety of cell types, CD4+ T cells, macrophages and DCs represent the three main targets of HIV-1 infection." (PMID 24009706, 2013). "ZFNs, which are engineered endonucleases containing zinc finger domains that recognize specific DNA sequences, have also been used to disrupt the CCR5 gene in CD4+ T-cells in a mouse model of HIV-1 infection." (PMID 23364195, 2013). "CD4+ T-cells are the major target for HIV-1 infection and both naïve and memory CD4+ T-cells have been shown to be permissive, with most viral DNA detected in CD4+ T-cells that express the memory marker CD45RO." (PMID 23818847, 2013). "On the basis of this data, we concluded that LAINeffs∆-1 and LAINeffs∆-13 exhibited a specific loss of the CD4 downregulation activity and were potentially useful to investigate the impact of CD4 downregulation by Nef on HIV-1 infection in BLT mice." (PMID 24172637, 2013). "Various groups have engineered different strains of Lactobacillus to express CCR5/RANTES, CD4, cyanovirin-N, and fusion inhibitors, and tested their ability to prevent HIV-1 infection." (PMID 23840383, 2013). "DCs have important roles in HIV-1 infection in terms of disseminating the virus to CD4+T cells but also in initiating adaptive immune responses against the virus." (PMID 23527130, 2013). "Scid-hu thy/liv mice were primarily used as an Invivo model of HIV-1 infection that targets mainly CD4+ T cells and monocytes/macrophages." (PMID 25436886, 2013). "HIV-1 infection is characterized by rapid and extensive CD4+ T-cell depletion and eventual immunodeficiency." (PMID 23658782, 2013). "After deposition of HIV-1 on the recipient mucosa, the infectious virus must cross the mucosal epithelium and interact with resident CD4+ T lymphocytes, macrophages and dendritic cells (DCs), the three major targets of HIV-1 infection." (PMID 24009706, 2013). "After expansion in vitro, the adenovirus-ZFN transduced CD4+ T cells were infused into humanized mice where they were able to establish resistance to HIV-1 infection." (PMID 24284874, 2013). "To investigate this, we analyzed the susceptibility of HLA-G+ CD4 Treg to X4- or R5-tropic HIV-1 viruses, or to a VSV-G-pseudotyped HIV-1 construct causing single-round HIV-1 infection." (PMID 23382678, 2013).
HIV-1 infection (continued). "PCR assays are now also being used to quantify HIV-1 DNA in CD4+ T cells from the gut associated lymphoid tissue (GALT), where the frequency of HIV-1 infection is generally higher than in the blood." (PMID 23459007, 2013). "Another report showed a correlation between viral load and the broadly neutralizing antibody response, as well as an inverse correlation between CD4 count and such an antibody response, in the early phase of HIV-1 infection." (PMID 23308290, 2013). "M1 and M2 human macrophages showed restriction against HIV-1 infection by inducing factors like APOBEC3G or reducing the expression of certain receptors (CD4) respectively." (PMID 24070317, 2013). "This reporter virus was then used to establish a latent HIV-1 infection in primary human CD4+ T cells, isolated from peripheral blood mononuclear cells (PBMCs) collected from healthy donors, via two distinct methods." (PMID 24156270, 2013). "During progressive HIV-1 infection, the relative frequency of classical Treg is increased, while their absolute counts are reduced as a consequence of lower total CD4 T cell counts." (PMID 23382678, 2013). "By interacting with key structural elements of HIV-1 Env near the apex at its membrane-distal end, these antibodies can interfere with binding to CD4, the receptor on T cells that is required for HIV-1 infection." (PMID 23658524, 2013). "For instance, in HIV-1 infection, the number of IKpDCs was correlated to CD4 depletion and disease progression." (PMID 23755314, 2013). "Although autophagy also functions as an intracellular host defense mechanism against viruses, it can be usurped by HIV-1 infection, particularly in macrophages and CD4+ T cells." (PMID 24278768, 2013). "This receptor was also the first identified receptor for human immunodeficiency virus (HIV-1) infection of CD4+ lymphocytes and CXCL12 was able to inhibit infection by T-tropic HIV-1 of HeLa-CD4 cells." (PMID 23322021, 2013). "By doing so, we found a trend for a faster CD4 cell count decline in MSM with newly acquired HIV-1 infection between 2003 and 2007 compared to the pre-cART era." (PMID 23724048, 2013). "We thus explored the capacity of purified CD8+ T-cells from 48 patients from the ANRS 147 OPTIPRIM study to suppress HIV-1 infection of autologous CD4+ T-cells ex vivo." (PMID 23555774, 2013). "Polarizing cytokines affect HIV-1 replication efficiency in macrophages; IFN-γ and TNF-α induce activation of the M1 subset of MDM, with downregulation of CD4 and consequent resistance to HIV-1 infection." (PMID 24278768, 2013). "In HIV-1 infection, binding of the virus to CD4+ T cells initiates an early actin polymerization in T-cells followed by depolymerization, a process mimicking the chemotactic response initiated from chemokine receptors." (PMID 23294842, 2013). "In human HIV-1 infection robust HIV-1-specific CD4 T cell responses, measured by their proliferative capacity, their functional avidity, their cytokine secretion potential, and their frequencies, are associated with low HIV-1 plasma viral loads." (PMID 23717308, 2013). "Chronic HIV-1 infection is characterized by progressive depletion of total CD4+ T-cells and persistent immune activation, events that are only partially controlled by antiretroviral therapy (ART)." (PMID 24147117, 2013). "This was supported by our in vitro findings that hCD4/R5/cT1 CD4+ T cells developed markedly lower and less sustained in vitro HIV-1 infection as compared to hCD4/R5/cT1 myeloid-lineage cells or primary human CD4 T cells." (PMID 23691059, 2013). "Recently, IL-27 has been shown to be a potent inhibitor of HIV-1 infection in CD4+ T cells and macrophages." (PMID 23527130, 2013). "First, we tested the effect of three MTB crude subcellular fractions, i.e. whole cell lysate, cell wall and culture filtrate proteins on HIV-1 infection in CD4+ cells activated with anti-CD3 by measuring intracellular p24 expression by flow cytometry." (PMID 24282561, 2013).
HIV-1 infection (continued). "CD8+ T-cells from two patients with PHI stood out for their strong capacity to suppress HIV-1 infection of autologous CD4+ T-cells, at levels similar to those found in HIC." (PMID 23555774, 2013). "This suggests that CA exerts opposite effects on the ability of macrophages and DCs to transmit HIV-1 infection to CD4+ T cells." (PMID 24009706, 2013). "The reduced capacity of hCD4/R5/cT1 mouse CD4+ T cells relative to the mouse myeloid-lineage cells to support productive HIV-1 infection is likely due to additional HIV-1 replication blocks reported in mouse T cells." (PMID 23691059, 2013). "Various key features of human HIV-1 infection, including selective depletion of CD4+ T cells, were reproduced in scid-hu thy/liv mice." (PMID 25436886, 2013). "HIV-1 infection of target cells is mediated via the binding of the viral envelope protein, gp120, to the cell surface receptor CD4." (PMID 24304511, 2013). "Of note, these detrimental immune responses after HIV-1 infection are triggered by accumulation of incomplete viral reverse transcripts, which likely contribute to the depletion of CD4+ T-cells in HIV-1 infected individuals." (PMID 24523981, 2013). "HIV-2 infection is characterized by an overall slower progression rate, lower viral loads, and higher CD4+ T-cell numbers than HIV-1 infection." (PMID 24133492, 2013). "CD40L is expressed on activated CD4+ T cells, which are abundant throughout chronic immune activation that is prevalent in HIV-1 infection." (PMID 24278768, 2013). "An inactive form of APOBEC3G can be found in tissue resident naïve or memory CD4+ T cells, which are permissive to HIV-1 infection." (PMID 23803414, 2013). "Optimizing therapeutic strategies for an HIV cure requires better understanding the characteristics of early HIV-1 spread among resting CD4+ cells within the first month of primary HIV-1 infection (PHI)." (PMID 23691172, 2013). "Conversely, the lower cortical actin density in naïve CD4+ T cells restricted viral antigen transfer and consequently HIV-1 infection." (PMID 24244453, 2013). "Activated CD4+ T lymphocytes, both during mono- or co-infection, are the primary targets of HIV-1 infection, though HIV-1 remains quiescent within the resting CD4+ T lymphocytes." (PMID 24023789, 2013). "Recently it was reported that follicular memory CD4+ T cells defined as CXCR5+PD-1+Bcl-6+ are a major compartment for HIV-1 infection in viremic hosts." (PMID 24278768, 2013). "We also tested the impact of the interaction CD85j/S100A9 in the NK cell-mediated control of HIV-1 infection in purified autologous CD4+ T cells by pre-stimulating NK cells with exogenous S100A9 proteins." (PMID 24156302, 2013). "As the goal was to eventually investigate the role of IL-27 in DCs with regard to HIV-1 infection, IL-27 treated DCs were also profiled and found to have similar levels of CD4, CCR5 and CXCR4 as iDCs or mDCs." (PMID 23527130, 2013). "It is conceivable that restriction to HIV-1 infection of myeloid cells and resting CD4+ T-lymphocytes is a means of innate or intrinsic immunity against retroviral infection in vivo." (PMID 24523981, 2013). "The introduction of ART into clinical practice has modified the natural course of HIV-1 infection, resulting in the decrease of HIV-1 plasmaviremia, increase in CD4 T lymphocytes, and decrease in HIV-1-associated opportunistic infections." (PMID 24151490, 2013). "We previously reported that Syk is important for an efficient HIV-1 infection of iDCs and subsequent virus transfer to CD4+ T cells." (PMID 23844079, 2013). "ATRA and LXR-agonist TO-901317 have synergistic effect on the induction of ABCA1 expression as well as anti-HIV-1 infection in CD4+ T cells." (PMID 22676378, 2012). "Quiescent CD4+ T lymphocytes are highly refractory to HIV-1 infection due to a block at reverse transcription." (PMID 23092122, 2012).
HIV-1 infection (continued). "The results obtained from the primary CD4+ T-cells confirmed our findings in PBMCs and provided corroborative evidence that Vpr enhances single-cycle HIV-1 infection." (PMID 22570689, 2012). "Several studies have assessed the molecular biology of the virus in this cell type, and a number of differences towards HIV-1 infection of CD4+ T cells have been described." (PMID 23035819, 2012). "Mucosal mononuclear (MMC) CCR5+CD4+ T cells of the gastrointestinal (GI) tract are selectively infected and depleted during acute HIV-1 infection." (PMID 22319447, 2012). "Cell-to-cell transfer is an important mode of HIV-1 dissemination within the host; for CD4+ T-cells, intercellular transfer is 2 to 3 logs more efficient at supporting viral replication than HIV-1 infection with cell-free inoculum." (PMID 22534017, 2012). "Resting CD4+ T cells in human tonsil explants undergo productive HIV-1 infection, in a manner dependent on the presence of the tissue microenvironment." (PMID 23170164, 2012). "Here, we demonstrate that HD5 inhibits HIV-1 infection of primary CD4+ T lymphocytes at low micromolar concentration under serum-free and low-ionic-strength conditions similar to those occurring in mucosal fluids." (PMID 23028850, 2012). "As the CD4 T cell count in peripheral blood is integral to the clinical monitoring of HIV-1 infection, it often goes unappreciated that the vast majority of CD4+ T cells are found in lymphoid tissues." (PMID 23170164, 2012). "HIV-1 infection results in altered MTB-specific memory CD4+ T cells at the disease site towards a less differentiated phenotype lacking the CCR5 receptor." (PMID 22215422, 2012). "In HIV-1 infection, however, the virus cannot be eliminated and thus propagates continuous immune activation concomitant with a CD4+ T cell decline." (PMID 22470494, 2012). "It has been proposed that α4β7 interactions play a major role in facilitating HIV-1 infection by enabling HIV-1 virions to target activated CD4+ T-cells." (PMID 22720026, 2012). "CXCR4- and CCR5- tropic HIV-1 infection was effectively inhibited in hu-BLT mouse spleen-derived human CD4+ T-cells ex vivo." (PMID 23300932, 2012). "The role of Th17 responses in immunity to mucosal acquired HIV-1 infection is unclear, however progressive HIV disease is associated with preferential depletion of CD4 Th17 cells." (PMID 22829921, 2012). "Two recent studies revealed that SAMHD1 restricts HIV-1 infection in resting CD4+ T-cells, providing new insights into the mechanisms of HIV-1 restriction in non-cycling cells." (PMID 23092163, 2012). "HIV-1 infection and replication is productive in activated CD4+ T cells and differentiated macrophages." (PMID 24832049, 2012). "CCR5 levels on CD4+ CM subset was higher in the CD4 Low group compared with the CD4 High group during the 1st year of HIV-1 infection." (PMID 23185351, 2012). "The macrophages, dendritic cells (DCs), and CD4+ T lymphocytes are considered reservoirs for HIV-1 infection." (PMID 22548060, 2012). "We show that Nef promotes DC-mediated HIV-1 transmission to activated CD4+ T cells, and that Nef expression promotes activation and proliferation of resting CD4+ T cells to enhance HIV-1 infection of these cells." (PMID 22479639, 2012). "It is well known that HIV-1-infected memory CD4+ T cells are severely depleted in number during the acute phase of an HIV-1 infection." (PMID 22880104, 2012). "On the other hand, HIV-1 infection of CD4+ T cells has a profound effect in impairing adaptive immune responses towards HCV infected cells contributing to poor natural clearance of the virus." (PMID 23202492, 2012). "Few studies have examined the impact of HIV-1 infection with CD4 counts above 200 cells/μl in sub-Saharan Africa." (PMID 23130818, 2012). "In the early stages of HIV-1 infection, the majority of CD4+ T cells are naïve and resting, and can be latently infected by HIV-1." (PMID 22479639, 2012).